PGR (progesterone receptor)
Diseases named in the same sentence as PGR in open-access papers (continued):
Sharing a sentence is not in itself a finding about the gene and the disease.
breast tumors (continued). "Our findings hypothesize associations between different lipoprotein subfractions, and PgR expression, and Ki 67 % in breast tumors." (PMID 26970778, 2016). "The differential regulation of ER may explain the occurrence of ER-/PgR+ breast tumors in younger women." (PMID 26161666, 2015). "Her breast tumor was estrogen-/progesterone-receptor (ER/PR) positive." (PMID 26114020, 2014). "For breast tumours, ER or progesterone receptor (PR) negative samples displayed higher risk score values than the positive ones, in line with their highest aggressive behavior." (PMID 22880004, 2012). "Breast tumors are currently characterized in the clinic based on tumor size, visual characteristics, and a limit number of histochemical markers including estrogen receptor, progesterone receptor, and HER2 receptor status." (PMID 21672245, 2011). "In light of recent evidence indicating that the 4ICD coactivator is an important effector of tumor response to tamoxifen and possibly fulvestrant, 4ICD coregulation of PgR expression in breast tumors could have important clinical implications." (PMID 20550710, 2010). "This variability in the ER isoform profile of breast tumours and their correlation with PgR levels may have a bearing on prognosis and tumour response to endocrine therapy." (PMID 1457348, 1992). "However, for patients with breast tumors expressing low levels of HR, categorically defined as 1–9% of ER or 1–20% of PgR, it is recommended to add more aggressive treatments such as chemotherapy, with endocrine therapy, for the oncologic safety of the patients." (PMID 34638491, 2021). "Interestingly, elevated FAM83B expression is associated with estrogen-receptor (ER) and progesterone-receptor (PR) negative breast tumors, an aggressive subtype for which currently no targeted therapies exist." (PMID 27221039, 2016). "In addition, 91% of the Thai breast tumors that were positive for any of the following receptors, estrogen receptor (ER), progesterone receptor (PR), and human epidermal growth factor receptor 2 (HER2) also expressed the AR protein, while in triple negative breast tumors only 33% were AR positive." (PMID 29083379, 2016). "Also, ERα methylation has associated to progesterone receptor negativity (p<0.008) and double receptor negative status (p<0.0001) in breast tumors." (PMID 23508069, 2012). "Doctors categorize breast tumors according to their appearance under a microscope, as well as the presence of three important proteins: HER2 (a growth-promoting protein), progesterone receptor (PR), and estrogen receptor (ER)." (PMID 41283276, 2025). "Breast tumors may be basal or luminal (type A or type B), but they also have a basic classification of subtypes based on their expression of three different tissue receptors: estrogen receptor (ER), progesterone receptor (PR), and human epidermal growth receptor 2 (HER2)." (PMID 36652113, 2023). "Estrogen receptor (ER), progesterone receptor (PR), and human epidermal growth factor receptor 2 (HER2) are involved in determining the subtypes, and more than 70% of breast tumors are found to express ER." (PMID 35948548, 2022). "Several studies have reported varying discordance rates for the estrogen receptor (ER), progesterone receptor (PR), and HER2 status between primary breast tumor and loco-regional or distant recurrences." (PMID 35025003, 2022). "Pathological biomarkers, including estrogen receptor (ER), progesterone receptor (PR) and HER2 (human epidermal growth factor receptor 2) provide the clinical basis for classifying breast tumors and directing therapeutic strategies." (PMID 34638293, 2021). "Breast tumours with high Notch3 levels are enriched in the triple-negative breast cancer (TNBC) subclass that lacks estrogen receptor, progesterone receptor (PR) and human epidermal growth factor receptor 2 (Her2) expression." (PMID 32210034, 2020).
breast tumors (continued). "In our cohort, 424 women with personal history of breast cancer had estrogen receptor (ER), progesterone receptor (PR), and human epidermal growth factor receptor 2 (HER2) expression status of the breast tumor available." (PMID 31308460, 2019). "Common screening markers for suspected breast tumors include the expression of cytokeratin, CK-7, CK-18, CK-19, CK-20, GCDFP-15, and ER/PgR." (PMID 29987656, 2018). "They indicated that most responsive breast tumors had the highest expression of Keratin 5/7 (KRT5/KRT17) and the lowest expression of endogen receptor (ER), progesterone receptor (PR) or human epidermal growth factor receptor-2 (HER2)." (PMID 28446239, 2017). "The data show that more breast tumors contain elevated BST-2 protein compared with the levels of estrogen receptor, progesterone receptor, HER2 or Myc." (PMID 28300825, 2017). "An immunohistochemical analysis of the breast tumor showed ER (+), PgR (+), HER2 (3+), and E-cadherin (−), while that of the appendiceal tumor showed ER (+), PgR (−), HER2 (3+), and E-cadherin (−)." (PMID 27683008, 2016). "If the presence of functional ERs is so important for tissue invasion in several breast tumor types, a plausible question is whether the efficacy of conventional hormonal therapy is compromised in patients with dysfunctional ERs (those patients with the ER+PgR− tumor phenotype)." (PMID 24917206, 2014). "TNBC is a breast tumour subtype that is negative for estrogen receptor (ER), progesterone receptor (PR), and human epidermal growth factor receptor-2 (HER2) expression." (PMID 40136327, 2025). "This revealed that both EPI (e.g. LLGL2, CLDN4, KRT7, ST14) and MES (e.g. SNAI1, VIM, AP1M1) genes positively correlated with PIEZO1 expression across all quintiles, whilst markers of luminal breast tumors (ESR1, FOXA1, PGR) negatively correlated in all instances." (PMID 38632473, 2024). "It is a heterogeneous disease classified into different molecular subtypes based on the presence (+) or absence (-) of immunohistochemical markers such as ER (estrogen receptor), PR (progesterone receptor), and HER2/neu (human epidermal growth factor receptor 2) in the breast tumour." (PMID 38022682, 2023). "Analysis of primary breast tumors revealed that miR-489 expression positively correlated with the expression of CALCR, ESR1, and ER-responsive genes such as progesterone receptor (PGR), suggesting that miR-489 expression may be regulated by estrogen signaling." (PMID 35897675, 2022). "Our analysis of breast tumor transcriptome datasets, however, revealed that in tumors with lower PGR expression, the clinical PR status does not correlate accurately with the expression of ESR1 or of ER target genes, including PGR itself." (PMID 36358871, 2022). "In concordance with this finding, PD-L1 expression is reportedly the highest in ER/PgR negative breast tumors." (PMID 35226658, 2022). "TN breast tumors are negative for estrogen receptor (ER), progesterone receptor (PR), and amplification of the human epidermal growth factor receptor 2 (HER2)." (PMID 36077608, 2022). "IHC is currently the gold standard method in routine pathological diagnosis, including the semiquantitative determination of Estrogen Receptor 1 (ESR1), Progesterone Receptor (PGR) and Human Epidermal Growth Factor Receptor 2 (HER2) receptor status in breast tumors." (PMID 34408238, 2021). "In parallel, we investigated TREM-1 expression directly by immunofluorescence staining using a breast tumor tissue microarray consisting of >40 invasive ductal and lobular carcinomas positive or negative for the clinical markers ER, PGR and HER-2." (PMID 34956864, 2021). "Nonetheless, in PgR(−) breast tumors, PGR methylation is usually either low or absent, so hypermethylation of PGR promoter is unlikely the major mechanism of PgR silencing, albeit some data are contradictory." (PMID 34638241, 2021).
breast tumors (continued). "Triple-negative breast cancer (TNBC) is defined as a breast tumor lacking the expression of estrogen receptor (ER), progesterone receptor (PR), and human epidermal growth factor receptor-2 (HER2)." (PMID 34895326, 2021). "Based on the expression of estrogen receptor (ER), progesterone receptor (PgR), and ERBB2 (HER2), breast tumors are classified as luminal A, luminal B, HER2, and basal-like or triple-negative (TNBC), which exhibit different tumor aggressiveness and response to therapy." (PMID 33230261, 2021). "The hormone-positive subtype, characterized by the expression of the estrogen receptor with or without the progesterone receptor (ER+/PR+/−), represents ~65% of breast tumours." (PMID 34572926, 2021). "Gene expression analysis showed that MIAT was upregulated in estrogen receptor (ER), progesterone receptor (PR), Erb-B2 Receptor Tyrosine Kinase 2 (HER2) positive breast tumors suggesting that lncRNAs play crucial roles in cell proliferation by targeting the CDKN2A locus." (PMID 31141943, 2019). "All three steroid receptors analyzed by immunohistochemistry, namely, the estrogen receptor (ER), the progesterone receptor (PR), and the vitamin D receptor (VDR), showed a significantly positive influence on the course of the disease, but only for the unifocal breast tumor patients." (PMID 31731733, 2019). "Only two percent of the ERα(-) breast tumors not overexpressing Her-2 are positive for the progesterone-receptor." (PMID 30687231, 2018). "A possible interpretation is that ER + PgR+ and ER negative breast tumors are intrinsically so different that the HER2 overexpression reduces number of LMA ER + PgR+ tumors and HMA ER-PgR- tumors." (PMID 28356061, 2017). "Cluster 1 was enriched with hormone receptor‐negative (e.g., ER‐, PgR‐, and HER2‐) and samples with high TILs, which suggests that microRNAs detected in the interstitium are associated with breast tumor subtype, as well as immune response." (PMID 28145100, 2017). "Triple-negative breast cancers (TNBCs) are defined as a subset of breast tumors with absent or low levels of estrogen receptor (ER), progesterone receptor (PR), and HER2 expression." (PMID 28415760, 2017). "As the name implies, triple-negative tumors represent a subset of breast tumors that are negative for the estrogen receptor (ER), progesterone receptor (PR), and human epidermal growth factor receptor-2 (HER2)." (PMID 28887687, 2017). "For example, protein levels of CCNB1 (cyclin B1) were significantly higher (P = 7.28E‐13) in breast tumors with alterations in FAM83 family genes, whereas protein levels of GATA3 (P = 3.79E‐07), PGR (P = 5.77E‐07), and ESR1 (P = 9.20E‐07) were significantly lower." (PMID 28078827, 2017). "miR-30 family members, including miR-30a, are downregulated in estrogen receptor–negative and progesterone receptor–negative breast tumors, suggesting that these hormones are involved in de novo synthesis of miR-30 family members." (PMID 26918943, 2016). "The level of SRA is increased in breast tumors and the expression of SRA correlates with estrogen receptor (ER) and progesterone receptor (PR) levels, which may alter ER/PR action and promote tumorigenesis." (PMID 26967566, 2016). "This differential expression of the INHBA was not dependent on the category of breast tumors such as estrogen receptor, progesterone receptor, or Her2 status." (PMID 28721365, 2015). "For example, one-third of ER+/progesterone receptor-positive (PGR+) breast tumors treated with TAM do not respond to initial treatment, and the remaining 70% are at risk to relapse in the future." (PMID 25971350, 2015). "One-third of estrogen (ER+) and/or progesterone receptor-positive (PGR+) breast tumors treated with Tamoxifen (TAM) do not respond to initial treatment, and the remaining 70% are at risk to relapse in the future." (PMID 25971350, 2015).
breast tumors (continued). "Thismixed luminal/basal pattern has been reported to occur in one quarter of primaryoperable breast tumors.Interestingly, the cells were positive for ERα and Ki67 but negative for PGR(the PGR stain is negativerelative to controls cells on the same section)." (PMID 25527189, 2014). "In our stratified univariate analysis the prognostic value of nuclear YB-1 expression became even more pronounced in the clinically important subgroup of stage pT1/T2 tumors and breast tumors with negative progesterone receptor status, respectively." (PMID 19930682, 2009). "In a similar comparison nuclear YB-1 protein was not detectable in most progesterone receptor positive breast tumours, while there was prominent nuclear YB-1 staining in most tumors with negative progesterone receptor status (D)." (PMID 19930682, 2009). "Other subsets of tumors such as the so-called 'triple-negative' breast tumors, ERα-/progesterone receptor-negative (PR-)/Her2-, remain difficult to treat." (PMID 18534028, 2008). "The triple-negative classification refers to breast tumors lacking expression of the receptors ER (estrogen receptor), PR (progesterone receptor), and HER2/neu (human epidermal growth factor receptor 2), which are commonly used as therapeutic targets for systemic treatments." (PMID 37760847, 2023). "Based upon immunohistochemical staining for key proteins’ expression, breast tumors are considered to contain at least 1% of the following genes: human epidermal growth factor receptor 2 (HER2, Erbb2 gene), estrogen receptor (ER), and progesterone receptor (PR, Pgr gene)." (PMID 37153758, 2023). "76% of the breast tumors from PV carriers were estrogen and progesterone-receptor-negative." (PMID 35039532, 2022). "Patients with ERα- and progesterone-receptor negative breast tumors expressing ERβ1 presented with a better prognosis irrespective of whether the tumors expressed Her-2 or not." (PMID 30687231, 2018). "Interestingly, tumor samples with a breast tumor type categorized as luminal B and an ERα+/PGR− receptor status demonstrated high AGO2 expression levels compared to samples with luminal A/ERα+/PGR+ receptor status." (PMID 29657266, 2016). "In addition to morphological profiling, immunohistochemical analyses for specific markers—including estrogen receptor (ERα), progesterone receptor (PR), and human epidermal growth factor receptor 2 (HER2/NEU/ERBB2)—have allowed breast tumors to be classified into different subtypes." (PMID 27110512, 2016). "For example, breast tumors are commonly assessed for three receptors that are used as pathological biomarkers: the presence or absence of estrogen receptor (ER) and progesterone receptor (PR), and the enrichment of human epidermal growth factor receptor 2 (HER2 or ERBB2)." (PMID 25541715, 2014). "The present clinical study was undertaken to determine whether the expression of ER, PgR, HER2, P-gp, MRP, GST-pi and Topo-II could affect the pathologic response of primary breast tumors to three different preoperative chemotherapy regimens including DEC, VFC and EFC." (PMID 19591668, 2009). "In a stratified univariate analysis, the prognostic value of nuclear YB-1 detection became even more pronounced in the clinically important subgroup of stage pT1/T2 tumors, representing ~80% of all diagnosed carcinomas, and breast tumors with negative progesterone receptor status." (PMID 19930682, 2009). "Previous studies have suggested that patients with ER-positive and PgR-positive breast tumours have a more active ER and have demonstrated that these patients are more likely to benefit from endocrine therapy compared with patients with ER-positive/PgR-negative tumours." (PMID 15094759, 2004). "Immunophenotypic analysis identify a particular breast tumor subtype, defined TNBC, because it do not express ER and PgR hormone receptors and shows non-overxepressed/amplified HER-2 oncogene." (PMID 26504780, 2015).
breast tumors (continued). "Breast tumors lacking BRCA-1 tend to be triple-negative (TNBC) basal-like characterized by reduced expression of estrogen receptor-α (ERα), progesterone receptor (PR), and epidermal growth factor receptor-2 (HER-2)." (PMID 26715507, 2015). "Similar results were obtained by Tramm and colleagues who showed that the surrounding non-neoplastic tissue does not affect the quantification of ESR1, PGR, and ERBB2 mRNA expression in breast tumor samples." (PMID 25218890, 2014). "After obtaining informed consent from three patients with oestrogen and progesterone receptor positive and HER-2/neu negative invasive ductal adenocarcinoma of the breast, tissue specimens were obtained during breast tumour excision." (PMID 20051100, 2010).